SCAT2 (S-phase cancer associated transcript 2)
Synonyms: CBX5-AS1; AC078778.1
Gene: Long non-coding RNA gene on chromosome 12 (54,262,597 to 54,279,063, forward strand). Ensembl gene ENSG00000257596.
Diseases named in the same sentence as SCAT2 in open-access papers:
SCAT2 is named in the same sentence as 1 disease in open-access papers, as found by Europe PMC text mining. Sharing a sentence is not in itself a finding about the gene and the disease. The quoted sentences say what the papers report.
tumor (3 papers, 2022 to 2023). "In cervical cancer, AL441992.1, LINC01305, AL354833.2, lncRNA CNNM3-DT and lncRNA SCAT2 can promote cuproptosis to protect the body from tumor cells attack and improve tumor prognosis; while AL354733.3 and AC009902.2 can inhibit cuproptosis to facilitate tumor growth." (PMID 37313458, 2023). "Among the lncRNAs, eight were overexpressed in tumor tissues (SNHG3, AC099850.4, MIR17HG, AL033527.3, AC091057.1, AC026333.4, AL512506.1, and SCAT2)." (PMID 35778697, 2022). "The results showed that AC009902.2 and AL354733.3 were significantly upregulated in tumor cells compared with normal tissues, whereas AL441992.1, LINC01305, AL354833.2, CNNM3-DT, and SCAT2 were downregulated in CC cells." (PMID 36204323, 2022).